ABCB10 (ATP binding cassette subfamily B member 10)
Description:
ATP-dependent transporter located in the mitochondrial inner membrane that catalyzes the export of biliverdin from the mitochondrial matrix, and plays a crucial role in hemoglobin synthesis and antioxidative stress. Participates in the early step of the heme biosynthetic process during insertion of iron into protoporphyrin IX (PPIX). Involved in the stabilization of the iron transporter mitoferrin-1/SLC25A37 (By similarity). In addition may be involved in mitochondrial unfolded protein response (UPRmt) signaling pathway, although ABCB10 probably does not participate in peptide export from mitochondria.
Synonyms: M-ABC2; EST20237; MTABC2
Tractability: Small molecule: a structure with a bound ligand is known; it has a binding pocket of medium quality. Antibody: UniProt predicts a signal peptide or a membrane-spanning region. PROTAC: ubiquitination databases record sites on it; its protein half-life has been measured.
Gene: Protein-coding gene on chromosome 1 (229,516,582 to 229,558,957, reverse strand). Ensembl gene ENSG00000135776.
Subcellular location: Mitochondrion inner membrane
Pathways (Reactome):
Transport of small molecules: Mitochondrial ABC transporters
Gene Ontology:
Molecular function: ABC-type transporter activity; ATP hydrolysis activity; protein binding; protein homodimerization activity; ATP binding; identical protein binding
Biological process: erythrocyte development; export from the mitochondrion; mitochondrial unfolded protein response; positive regulation of hemoglobin biosynthetic process; heme biosynthetic process; mitochondrial transport; positive regulation of erythrocyte differentiation; positive regulation of heme biosynthetic process; transmembrane transport
Cellular component: ATP-binding cassette (ABC) transporter complex; mitochondrial membrane; mitochondrion; mitochondrial inner membrane; membrane
Genetic constraint (gnomAD): Loss-of-function variants: 54 observed, 59.34 expected, observed/expected ratio (o/e) 0.91, 90% interval 0.73 to 1.14. The upper end of that interval is the gene's LOEUF score, 1.14, which puts it in group 5 of 6, group 1 being the genes least tolerant of losing a copy. Missense variants: 838 observed, 866.27 expected, observed/expected ratio (o/e) 0.97, 90% interval 0.91 to 1.02. Synonymous variants: 413 observed, 355.13 expected, observed/expected ratio (o/e) 1.16, 90% interval 1.07 to 1.26.
Homologues: Orthologues: chimpanzee ABCB10 (99% identical), macaque ABCB10 (96% identical), dog ABCB10 (85% identical), pig ABCB10 (83% identical), rabbit ABCB10 (77% identical), guinea pig ABCB10 (75% identical), rat Abcb10 (72% identical), mouse Abcb10 (71% identical), tropical clawed frog abcb10 (59% identical), zebrafish abcb10 (57% identical), Drosophila melanogaster CG3156 (42% identical), Caenorhabditis elegans pgp-1 (31% identical), and 8 more. Paralogues in human: ABCB8 (33% identical), ABCB9 (32% identical), ABCB1 (30% identical), ABCB4 (30% identical), ABCB5 (30% identical), TAP1 (29% identical), ABCB11 (28% identical), TAP2 (28% identical), ABCB6 (24% identical), ABCB7 (22% identical).
Diseases named in the same sentence as ABCB10 in open-access papers:
ABCB10 is named in the same sentence as 48 diseases in open-access papers, as found by Europe PMC text mining. Sharing a sentence is not in itself a finding about the gene and the disease. The quoted sentences say what the papers report.
breast carcinoma (25 papers, 2007 to 2026). "ABCB10 plays a key regulatory role in sponging miR-1271 in vitro in a loss-of-function assay, where knockdown of circ-ABCB10 reduced cell proliferation and increased apoptosis in breast cancer cells." (PMID 37243750, 2023). "Beside circ-Foxo3, circ-ABCB10 is another circRNA associated with breast cancer." (PMID 29349062, 2017). "Liang and his colleagues, based on a circRNA microarray, have reported several aberrantly expressed circRNAs, including circ-ABCB10 in breast cancer cells." (PMID 39858015, 2025). "Dysregulated circRNA in breast cancer such as hsa circ _0008717 (circ-ABCB10) contributes to the proliferation by sponging miR-1271." (PMID 37243750, 2023). "In breast cancer, circ-ABCB10 acts as a miR-223-3p sponge and regulates the expression of the miR-223-3p targeted gene PFN2 to induce cell migration." (PMID 35646916, 2022). "Circ-ABCB10 has been identified as a breast cancer oncogene, and circ-ABCB10 knockdown suppresses proliferation and increases apoptosis in breast cancer cells." (PMID 35865469, 2022). "For example, circ-ABCB10 is highly upregulated in breast carcinoma, and the repression of circ-ABCB10 decreased tumorigenesis while enhancing apoptosis." (PMID 35885916, 2022). "The sponging of miR‐1271 and miR‐143 by circ‐ABCB10 and hsa_circ_0001982 has been demonstrated earlier with breast cancer." (PMID 33544410, 2021). "As reported, circ-ring finger protein 111 (circ-RNF111) and circ-ABCB10 enhanced PTX resistance in breast cancer." (PMID 34649611, 2021). "The oncogenic role of circ-ABCB10 in breast cancer and clear cell renal cell carcinoma has been validated in recent researches." (PMID 31931771, 2020). "Silencing of circ-ABCB10 promotes apoptosis of breast cancer cells and epithelial OC cells via decreased sponging of miR-1271, miR-1252 and miR-203." (PMID 32171304, 2020). "Previous findings showed that circ-ABCB10 was upregulated and served as an oncogene in several cancers such as clear cell renal cell carcinoma and breast cancer." (PMID 31931771, 2020). "Recently, existing literatures have uncovered the cancer-promoting role of circ-ABCB10 in clear cell renal cell carcinoma and breast cancer." (PMID 31931771, 2020). "For instance, circ-ABCB10 is noticeably up-regulated in breast cancer tissues and facilitates breast cancer cell proliferation." (PMID 33097010, 2020). "Circ-ABCB10 (hsa_circ_0008717), derived from a region in the ABCB10 gene, is highly expressed in breast cancer, epithelial ovarian cancer (OC) and HCC, which correlates with patient survival." (PMID 32171304, 2020). "Previous studies have revealed the cancer-promoting role of circ-ABCB10 in clear cell renal cell carcinoma and breast cancer." (PMID 31931771, 2020). "In a similar way, results of another study discovered a significantly up-regulated circRNA hsa_circ_0008717 in breast cancer tissue and they nominate it as circ-ABCB10." (PMID 30157902, 2018). "Studies have reported that ABCB5, ABCB8, ABCB10, ABCC2–5, and ABCC10 are overexpressed in breast cancer cells or are associated with breast cancer progression." (PMID 30202239, 2018). "In vitro, loss-of-function experiments showed circ-ABCB10 knockdown suppressed the proliferation and increased apoptosis of breast cancer cells, revealing the important regulatory role of circ-ABCB10 through sponging miR-1271." (PMID 30157902, 2018). "Circ-ABCB10 was significantly upregulated in breast cancer tissues, and its function as a sponge for miR-1271 has been determined." (PMID 29349062, 2017). "In addition, they also demonstrated that downregulation of circ-ABCB10 promotes G0/G1 arrest in breast cancer cells, followed by reduced clonogenicity and in vitro cellular proliferation." (PMID 39858015, 2025). "Circ-RNA of ABCB10 may provide paclitaxel resistance of breast cancer cells and cisplatin resistance of lung cancer cells." (PMID 40141294, 2025).
breast carcinoma (continued). "Furthermore, knockdown of circ-ABCB10 inhibits breast cancer cell proliferation and increased apoptosis, revealing an important regulatory role of circ-ABCB10 through sponging miR-1271." (PMID 37238729, 2023). "Circ-ABCB10 was found to promote the proliferation, migration, and metastasis of diverse cancers, such as esophageal squamous cell carcinoma, lung cancer, epithelial ovarian cancer, breast cancer, and hepatocellular carcinoma." (PMID 35646916, 2022). "In general, circ-ABCB10 can act as an oncogene by promoting tumor proliferation and migration in glioma, non–small cell lung cancer, esophageal cancer, breast cancer, and renal cancer and can also be an anti-oncogene by inhibiting the growth in hepatocellular carcinoma and cervical cancer." (PMID 35646916, 2022). "The antisense strand of Circ-ABCB10 undergoes back-splicing of the 5′ and 3′ ends to form circular RNA With specific expression in different developmental stages and tissues, Circ-ABCB10 was first reported to promote breast cancer proliferation and migration by sponging miR-1271." (PMID 35646916, 2022). "Circ-ABCB10 promoted the tumorigenesis of breast cancer via sponging miR-1271." (PMID 32847606, 2020). "Furthermore, in vitro circ-ABCB10 knockdown suppressed proliferation and increased apoptosis of breast cancer cells." (PMID 29349062, 2017). "Similarly, the presence of ABCB10 and NUP133, and candidate tumor suppressors LRRFIP1 and RNU3IP2 in the RB1-related cluster, further support their functional association in breast cancer." (PMID 17280605, 2007). "Similarly, it was also found that circ-ABCB10 can sponge miR-1271, which may have a complementary sequence, possibly regulating cell proliferation and migration of breast cancer and epithelial ovarian cancer cells." (PMID 35646916, 2022). "Through the let-7a-5p/DUSP7 axis, Circ-ABCB10 regulates PTX resistance, apoptosis, invasion, and autophagy in breast cancer cells." (PMID 35265667, 2022). "Circ-ABCB10 mediates the PTX resistance, apoptosis, invasion and autophagy of breast cancer cells through the let-7a-5p/DUSP7 axis." (PMID 32758239, 2020).
lung carcinoma (7 papers, 2020 to 2025). "To investigate the underlying mechanism of circ-ABCB10 in lung cancer, we carried out subcellular fractionation and FISH assays to investigate the localization of circ-ABCB10." (PMID 31931771, 2020). "Subsequently, we aimed to explore whether dysregulation of circ-ABCB10 was implicated in the sensitivity of lung cancer cells to cisplatin." (PMID 31931771, 2020). "Another previous study also discovered that knocking circular ABCB10 down boosted the susceptibility of lung cancer cells to cisplatin, implying that targeting circular ABCB10 could be a promising target for enhancing cisplatin’s effectiveness in lung cancer." (PMID 36650399, 2023). "Also, we validated via rescue assays that miR-556-3p participated in the regulation of circ-ABCB10 on lung cancer progression and sensitivity to cisplatin resistance of lung cancer cells, which also firstly linked miR-556-3p to lung cancer and drug sensitivity of lung cancer cells." (PMID 31931771, 2020). "Wu found that miR-556-3p is involved in regulating the sensitivity of circ-ABCB10 to lung cancer progression and resistance of lung cancer cells to cisplatin." (PMID 35290415, 2022). "It has been found that circ-ABCB10 can sponge miR-1252 and miR-584-5p in non–small cell lung cancer cells and accordingly stimulate the expression of the downstream targeted genes FOXR2 and E2F5." (PMID 35646916, 2022). "Cisplatin treatment abrogated lung cancer cell proliferation, and such effect was further enhanced by sh-circ-ABCB10#1 in A549 and NCI-H292 cells were treated with cisplatin." (PMID 31931771, 2020). "In sum, circ-ABCB10 is expressed at high levels and featured with circular structure in lung cancer; circ-ABCB10 deletion represses lung cancer progression whereas sensitizes lung cancer cells to cisplatin." (PMID 31931771, 2020). "In summary, all these data from this study indicate that targeting circ-ABCB10/miR-556-3p/AK4 pathway enhance sensitivity of lung cancer cells to cisplatin." (PMID 31931771, 2020). "Circ-ABCB10 knockdown enhances sensitivity of lung cancer cells to cisplatin by targeting miR-556-3p/AK4 axis." (PMID 31931771, 2020). "This study mainly focused on probing the regulatory mechanism of circ-ABCB10 and its influence on cell sensitivity to cisplatin in lung cancer." (PMID 31931771, 2020). "To further verify the effect that the circ-ABCB10 regulated lung cancer progression and sensitivity to cisplatin via interacting with miR-556-3p, we applied rescue assays in transfected cells treated with or without cisplatin." (PMID 31931771, 2020). "Circ-ABCB10 depletion suppresses lung cancer progression and sensitizes lung cancer cells to cisplatin." (PMID 31931771, 2020). "To uncover the effect of circ-ABCB10 on cellular sensitivity to cisplatin and lung cancer progression in vitro, we knocked down circ-ABCB10 in NCI-H292 and A549 cells." (PMID 31931771, 2020). "Next, CCK-8 and colony formation assays depicted that compared with that sh-circ-ABCB10#1 strikingly weakened the proliferation ability of lung cancer cells compared with sh-NC group." (PMID 31931771, 2020). "Further, we demonstrated that knockdown of circ-ABCB10 can further enhance the anti-proliferation and pro-apoptosis effect of cisplatin on lung cancer cells, suggesting that targeting circ-ABCB10 sensitized lung cancer cells to cisplatin in vitro." (PMID 31931771, 2020). "Concordantly, we showed that circ-ABCB10 was mainly distributed in cytoplasm of lung cancer cells, verifying that circ-ABCB10 played vital roles in lung cancer by post-transcriptionally regulating certain miRNA." (PMID 31931771, 2020). "Taken together, circ-ABCB10 directly interacts with miR-556-3p to regulate proliferation, migration, apoptosis, and sensitivity to cisplatin in lung cancer cells." (PMID 31931771, 2020). "Meanwhile, circ-ABCB10 could affect cisplatin sensibility in lung cancer through binding with miR-556-3p47." (PMID 37884630, 2023).
lung carcinoma (continued). "However, the overexpression of circ-ABCB10 was also found to inhibit the migration and invasion of lung cancer cells, hepatocellular carcinoma cells, and rectal cancer cells." (PMID 35646916, 2022). "The upregulation of circ-ABCB10 was found to promote cell proliferation in various tumors, including esophageal squamous cell carcinoma, esophageal cancer, glioma, non–small cell lung cancer, and oral squamous cell carcinoma." (PMID 35646916, 2022). "In comparison with that in control cells, the expression of circ-ABCB10 was significantly declined in cisplatin-treated cells rather than other drugs including 5-FU, Sorafenib, and Sunitinib, indicating that circ-ABCB10 was related to cellular response to cisplatin in lung cancer." (PMID 31931771, 2020). "However, the regulatory mechanism of circ-ABCB10 and its relation to cellular sensitivity to cisplatin in lung cancer is poorly understood." (PMID 31931771, 2020). "Furthermore, transwell assay demonstrated that the migration ability was weakened in lung cancer cells transfected with sh-circ-ABCB10#1 compared with sh-NC control." (PMID 31931771, 2020). "Circ-ABCB10 was markedly upregulated and featured with loop structure in lung cancer." (PMID 31931771, 2020). "More importantly, rescue assays clarified that upregulation of AK4 could reverse the cisplatin-sensitizing and tumor-suppressing effect of circ-ABCB10 knockdown on lung cancer cells." (PMID 31931771, 2020). "Notably, our data firstly showed that cisplatin treatment led to a decrease of circ-ABCB10 in lung cancer cells, indicating the involvement of circ-ABCB10 in the cellular response to cisplatin in lung cancer." (PMID 31931771, 2020). "Then, we further find out the miRNA related to circ-ABCB10 in lung cancer." (PMID 31931771, 2020). "Thus, we suspected that circ-ABCB10 played vital role in lung cancer via sponging specific miRNA." (PMID 31931771, 2020). "Circ-ABCB10 increases the expression of AK4, promotes lung cancer progression, and sensitizes lung cancer cells to cisplatin via sponging miR-556-3p." (PMID 36338714, 2022). "In addition, circ-ABCB10 was reported to sponge miR-145-5p, affecting the miR-620/FABP5 axis, miR-1252 FOXR2, and miR-670-3p in oral squamous cell carcinoma, glioma, non–small cell lung cancer, and esophageal squamous cell carcinoma, respectively." (PMID 35646916, 2022). "The results of this study elucidate that knockdown of circ-ABCB10 sensitized lung cancer cells to cisplatin via miR-556-3p/AK4 axis, which indicated that targeting circ-ABCB10 might be a new thought to improving the efficacy of cisplatin in lung cancer." (PMID 31931771, 2020).
cervical cancer (4 papers, 2021 to 2022). A primary or metastatic malignant neoplasm involving the cervix. "We focused on the detailed functions of circ-ABCB10 in cervical cancer (CC) development and its mechanisms." (PMID 34493213, 2021). "The circular RNA circ-ABCB10 is a strong promoter of tumorigenesis in breast and cervical cancer." (PMID 34884646, 2021). "Coincidentally, circ-ABCB10 can also regulate the proliferation and EMT of cervical cancer by inhibiting the miR-128-3p/ZEB1 axis." (PMID 35646916, 2022). "Our study suggests that circ-ABCB10 depletion inhibits proliferation, invasion and EMT and promotes apoptosis of cervical cancer cells through miR-128-3p/ZEB1 axis and represses CC tumor growth." (PMID 34493213, 2021). "Circ-ABCB10 acts as a sponge for miR-128, which in turn results in an increase in its direct target ZEB1, leading to augmented cell proliferation, migration, invasion, and inhibition of apoptosis in cervical cancer." (PMID 34884646, 2021).
anemia (3 papers, 2020 to 2024). A reduction in the number of red blood cells, the amount of hemoglobin, and/or the volume of packed red blood cells. "Loss of Abcb10 is embryonic lethal, and loss of Abcb10 in hematopoietic cells results in severe anemia." (PMID 37269954, 2023). "Abcb10 knockout mice shows severe anemia at day 10.5 of development, and it is embryonically lethal by day 12.5 of gestation." (PMID 37269954, 2023). "The ATP-binding cassette protein ABCB10 is essential for normal heme production, as knocking down this transporter in mice is embryonically lethal and accompanied by severe anemia plus oxidative damage." (PMID 33253225, 2020). "Other relevant findings include the low overall expression of membrane genes and genes involved in erythropoiesis (GATA1, ALAS2, ABCB10, and HEMGN) in CSA and overexpression in the rest of the congenital anemias studied compared to healthy controls." (PMID 39519257, 2024).
breast tumor (2 papers, 2019 to 2022). "It was reported that circ-ABCB10 increases breast tumor progression by sponging miR-1271." (PMID 35885916, 2022). "Among 200 hits, three genes (DEDD, ABCB10, and UAP1) are dysregulated (amplification and messenger RNA (mRNA) upregulation) in more than 40% of TNBC tumors and in 20% of all breast tumors examined." (PMID 31253784, 2019). "Interestingly, among the top dysregulated hits, a set of genes (DEDD, ABCB10, UAP1, KCNJ9, and PSAT1) are located close together on chromosome 1q23.3–42.1 and are co-amplified in >15% of breast tumors from 164 cancer genome studies." (PMID 31253784, 2019).
glioma (2 papers, 2021 to 2022). A benign or malignant brain and spinal cord tumor that arises from glial cells (astrocytes, oligodendrocytes, ependymal cells). "Multiple circRNAs, such as circ-TTBK2, circ-ABCB10 and circ_0001730, have demonstrated to play a crucial role in glioma via acting as competitive endogenous RNAs (ceRNAs)." (PMID 34727925, 2021). "At the same time, circ-ABCB10 can sponge miR-620 and upregulate the expression of the FABP5 axis to promote tumor growth and proliferation in glioma." (PMID 35646916, 2022).
hepatocellular carcinoma (2 papers, 2020 to 2022). A malignant tumor that arises from hepatocytes. "It is also seen in hepatocellular carcinoma that circ-ABCB10 can suppress the migration and metastasis by inhibiting the miR-340-5p/miR-452-5P—NRP1/ABL2 axis." (PMID 35646916, 2022). "However, in hepatocellular carcinoma, in vivo experiments indicate that circ-ABCB10 may be an anti-oncogenic factor." (PMID 35646916, 2022).